IL6 (interleukin 6)
Diseases named in the same sentence as IL6 in open-access papers (continued):
Sharing a sentence is not in itself a finding about the gene and the disease.
tumor (continued). "Clinical studies of an IL-6R inhibitor that inhibits the binding of IL-6 to its receptor, tocilizumab, have shown in patients with cancer cachexia the reduction of plasma IL-6 levels, the alleviation of muscle mass loss without affecting tumor proliferation." (PMID 30426026, 2018). "IL-6 stimulates the expression of adhesion molecules on the endothelial surface that could favour the adhesion of tumour cells." (PMID 29788918, 2018). "Considering these promising results, IL-6 promoter including rs1800795, rs1800796 and rs1800797 may be a tumor marker for cancer therapy." (PMID 29552316, 2018). "Previous studies showed that tumors produce tumor necrosis factor alpha, granulocyte colony-stimulating factor, interleukin-1 (IL-1), and IL-6, which may influence tumor-related SIR." (PMID 28744596, 2018). "Moreover, addition of IL-6 to tumor/NK cultures inhibited NK-mediated IFN-γ secretion in our previous studies." (PMID 29977235, 2018). "This protein is a key transducer signalling molecule for developing an immune response in a tumor setting and could be an antagonist of IL-6 activity since STAT3 is central to the IL-6 signalling pathway." (PMID 29854832, 2018). "Moreover, CSL when administered either alone or in combination with bortezomib inhibited MM tumor growth and decreased serum IL-6 and TNF-α levels." (PMID 29773987, 2018). "The KSHV viral homolog of interleukin-6 gene (vIL-6) may play a significant role in tumor development and may serve as a new anti-cancer target, but its role in tumor formation is only partially understood." (PMID 30265712, 2018). "The increase of IL-6 in the TME promotes tumor cell growth and disease progression." (PMID 30154786, 2018). "A large amount of cytokines secreted by the TME and tumor cells are involved in this process, including interleukin (IL)-6, transforming growth factor (TGF)-β, stromal-derived factor (SDF)-1, tumor necrosis factor (TNF)-α, interferon (IFN)-γ, macrophage inhibition factor (MIF), and IL-1α." (PMID 29386041, 2018). "IL-6 may also play an important role in various aspects of tumour behaviour, including apoptosis, tumour growth cell proliferation, migration and invasion, angiogenesis and metastasis." (PMID 29256156, 2018). "However, caloric restriction or reduction of TNFα and IL-6 leads to reduced tumor development in humans and mice by reducing colorectal inflammation." (PMID 30591653, 2018). "Another recent work performed in cell culture and mouse models suggests that tumour-derived IL-6 may be a candidate for inducing autophagy in more tissues distal tissues from the tumour." (PMID 29725601, 2018). "Analysis of the microarray data for the FAP+ TAM population isolated from 4T1 tumours revealed that these cells were also directly expressing some of the acute wound inflammatory response genes, including Il1b, Il6 and Osm, alongside the phenotypic markers Hmox1 and Fap." (PMID 30054470, 2018). "Therefore, we sought to block the STAT3 signaling pathway independently or in combination with conventional chemotherapy as a potential treatment strategy in tumors showing high levels of IL-6 in the tumor microenvironment." (PMID 29930760, 2018). "These immature MDSCs displayed a higher positive correlation with primary tumor size and the number of lung metastatic nodules in tumor-bearing mice than CD11b+Gr-1+ MDSCs, which is a major MDSC subset in primary tumors and more responsible for IL-6-stimulated tumor growth and metastasis." (PMID 30083161, 2018). "The expression levels of these cytokines were assessed in 4T1 tumours, which revealed a striking similarity to the reparative tissue response, including significantly higher Spp1, Il1b, Csf3, Il6 and Osm expression in 4T1 tumours compared to healthy mammary fat pad tissue." (PMID 30054470, 2018). "The NF-κB-dependent tumor growth factor released by IECs could be IL-6, which plays an important role in proliferation and can activates STAT3." (PMID 29464031, 2018).
tumor (continued). "To determine if tumor cells are a source of these cytokines, we analysed the effect of treatment with tumor cell-conditioned medium on cytokine levels and found a very similar inflammatory profile with elevated IL-1α, IL-6, MIP-1α and G-CSF." (PMID 30532184, 2018). "Consistently with other reports, we observed that the overexpression of RANTES did not affect the tumorigenesis of MCF-7 cells and MDA-MB-231 cells, whereas in MCF-7 cells IL-6 increased the rate of tumor growth as compared with control cells transfected with empty vectors." (PMID 29707128, 2018). "Although high-dose irradiation might directly inhibit functions of DCs, another study showed that irradiation (3 × 5 Gy) induced tumor cell death that triggers DC maturation and production of proinflammatory cytokines such as IL-6, IL-8, IL-12p70, and TNF-α." (PMID 28603525, 2017). "Here, we noted a particular decrease of IL-6 production, which might also contribute to alteration of tumor microenvironment by M1 transferring." (PMID 28243242, 2017). "SOCS3 expression moderately detected in vivo in BCC and SCC lesions can be influenced by the complex tumor microenvironment, where other cytokines, such as IL-6, could induce SOCS3 via STAT3." (PMID 28445952, 2017). "All these studies illustrated that TIM-3 may promote cancer progression through IL-6/STAT3 pathway or inhibiting IFN-γ production of effective T cells against tumor cells, exhibiting the function as a tumor-promoting role." (PMID 28423646, 2017). "However, all tumor cell lines co-cultured with MRC5 fibroblasts secreted high levels IL-6, CCL-2 and IL-8 and low levels of IL-10." (PMID 28750018, 2017). "It has been proposed that the high platelet count is the result of tumour-derived plasma interleukin-6 (IL-6), which can mediate the synthesis of thrombopoietin (a hormone responsible for regulating platelet production) in the liver to stimulate platelet production." (PMID 28737696, 2017). "Next, to test whether the overexpression of IL-6 promotes tumor metastasis in vivo, we established a tumor xenograft model, via the subcutaneous injection of the vector control or cells with IL-6 overexpression." (PMID 28208810, 2017). "In addition, the cytokines produced by activated innate immune cells in tumor microenvironment can stimulate tumorigenesis, such as IL-6 and TNF-α." (PMID 28630636, 2017). "Further, few of IL-6/GP130 inhibitors are efficient in suppressing tumor growth." (PMID 28430601, 2017). "As the key contributor in tumour microenvironment, CAFs secrete a number of factors such as cytokines, chemokines (e.g. IL-6, CXCL12), growth factors (e.g. HGF, transforming growth factor β, fibroblast growth factor) and receptors (e.g. platelet-derived growth factor receptor)." (PMID 28258248, 2017). "Finally, to determine the role of IL-6 and IL-8 in mediating the tumor-promoting effect of SHMT1, we performed rescue experiments." (PMID 28288142, 2017). "Furthermore, it was reported that in patients with GC, expression of IL-6 and STAT3 was increased in GC tumor tissue and that the level was associated with the TNM stage of GC." (PMID 28558708, 2017). "IL-6 is also important in recruiting immune cells into tumor microenviroment." (PMID 29242529, 2017). "In addition, treatment with laminarin among tumor-bearing mice increased production of IL-6, IL-12p40, and TNF-α in serum." (PMID 28423736, 2017). "IL-6 is a multifunctional cytokine that plays an important role in a wide range of biologic activities in different cell types, including inflammatory and tumor cells." (PMID 28418913, 2017). "There may also be constitutional symptoms in 50% of patients due to overproduction of interleukin 6 by the tumour cells." (PMID 27942694, 2017).
tumor (continued). "Tumor-free mice receiving only radiotherapy also demonstrated decreased cortical expression of IL-6, which has been widely recognized as one of the most important regulators of neuroimmune function and has been repeatedly associated with cancer-related neurological dysfunction." (PMID 27893434, 2017). "Furthermore, we demonstrate that the inhibition of tumor progression from DCIS to IDC is mediated by the suppression of local production of the inflammatory cytokines IL-6 and TNFα, within the tumor and mammary tissue." (PMID 28416734, 2017). "Untreated tumour mice had higher levels of serum IL-6 compared to control mice (P = 0.015)." (PMID 28120908, 2017). "Indeed, the levels of RNCR3 were markedly lower in the MDSCs isolated from bone marrow of IL-6 knockout (IL-6-/-) mice bearing B16 tumor than those in WT mice." (PMID 29340089, 2017). "The results showed that IL-6 enhanced the motility of tumor cells." (PMID 28846080, 2017). "In a Th1 microenvironment, proinflammatory cytokines (e.g., IL-6, IL-1α, and IL-1β) may contribute to tumour eradication by attracting leucocytes from the circulation and by increasing CD4 + T cell activity." (PMID 29089667, 2017). "It has been observed that the administration of 10 ng/ml of IL-6 increased the secondary mamospheres formation in normal and tumor mamospheres derived from the same patient (self-renewal capability), while the treatment of mamospheres with an anti-IL-6 antibody abolished the self-renewal capability." (PMID 28927416, 2017). "To explore the inflammatory stimuli from CTCs that stimulate G-CSF and IL-6 expression, we focused on the tumor cell-derived TLR2 and TLR4 (TLR2/4) ligands, since IL-37 could suppress TLR4 ligand-induced inflammatory response." (PMID 28415700, 2017). "We postulated that TLR4 knockout prevents the increase in circulating cytokines that could stimulate muscle catabolism such as TNFα, IL-6 and IL-1β, and determined the effect of TLR4 deficiency on circulating cytokines in LLC tumor-bearing mice." (PMID 28536426, 2017). "IL-6 has been reported to be a proliferative factor for diverse tumor types in vivo." (PMID 28545495, 2017). "Moreover, DC maturation is inhibited by the downregulation of the STAT3 pathway mediated by secretion of IL-6 by tumour cells." (PMID 28315228, 2017). "Notably, xenograft HNSCC tumors vascularized with IL-6-knockout endothelial cells exhibited slower tumor growth and smaller cancer stem cell fraction." (PMID 29245982, 2017). "Deletion of IL-6 reduced tumor numbers, tumor size, and tumor multiplicity." (PMID 28852270, 2017). "Specifically, higher concentrations of only the pro-inflammatory cytokine KC (murine IL8 homologue) was found in the spleen of both PANC-1 flank and orthotopic tumor-bearing groups when compared to sham, but only orthotopic tumor-bearing mice presented with higher concentrations of IL6." (PMID 27901481, 2017). "Interestingly, we found a higher inflammatory cell-infiltration in the native-ghrelin, but not In1-ghrelin, stably-transfected PC-3-tumors which, together with the increase in IL-6 expression, suggest a role of native-ghrelin in tumor inflammation." (PMID 28851363, 2017). "The oncogenic role of MALAT-1 may be partially mediated by TGF-β production because TGF-β can promote tumor cell growth by triggering interleukin-6 (IL-6) and vascular endothelial growth factor (VEGF) production." (PMID 28951743, 2017). "Binding of IL-6, IL-10, and IL-17 to their receptors promotes the activation of JAKs; however, the anti-tumor immunomodulatory role of IL-6, IL-10 and IL-17 remains unclear and appears contradictory in some aspects." (PMID 29262601, 2017).
tumor (continued). "The tumor-suppressive role of IL-6 may be further clarified by the outcome of an ongoing clinical trial combining DAC and Ruxolitinib, a JAK/STAT inhibitor [NCT02076191]." (PMID 29242529, 2017). "In both the in vitro tumor spheres and the in vivo murine model, there was a significant increase in the factors associated with M1 macrophage polarization, such as CCR5-binding chemokines (CCL3, CCL4, and CCL5), interleukins (IL-6 and IL-1β), and TNF-α." (PMID 28670313, 2017). "IL-6 has been shown to promote tumor growth in different types of cancer." (PMID 28915700, 2017). "Consequently, we combined IL-6 with growth-induced stress for tumor cells and found that solid stress enhanced EMT and stem-like properties induced by IL-6 in ccRCC via the Akt/GSK-3β/β-catenin signaling pathway." (PMID 28846080, 2017). "Tumor grade and IL-6 level remained significant factors for survival and event-free survival." (PMID 28851899, 2017). "TAMs are a source of tumour-promoting IL-6 in several murine tumour models." (PMID 28210073, 2017). "This is further supported by the demonstration that IL-6 blockade may reduce tumor cell viability while promotes apoptosis." (PMID 29268779, 2017). "Therefore, the preliminary in vivo study was conducted to the evaluate the effect of IL-6 on tumor growth and treatment application." (PMID 29100435, 2017). "Indeed, miR-204 expression decreased in tumor tissue obtained from IL-6-treated mice and in EOC cells exposed to IL-6." (PMID 28388577, 2017). "Our analyses confirmed that tumor size and IL-6 level were significant predictors of STS diagnosis." (PMID 28851899, 2017). "In contrast, the proinflammatory cytokines IL-6, IL-1α, and IL-1β may appear more unexpectedly as chronic inflammation related to the tumour." (PMID 29089667, 2017). "For example, TFs, such as ASH1L, CFLAR, HMGB3, ZNF160 and MATR3, displayed opposite behaviors on some cytokines; inflammatory factors; nuclear and tumor factors, such as IL-2, IL-6, NF-κB, and Irf3; immunogenic nucleic acids; papillomavirus E7/E6; caspase-3/caspase-8; Toll-like receptor; and so on." (PMID 28719625, 2017). "Inhibition of the IL-6 signaling by tocilizumab may block the amplifier circle and re-activate the anti-tumor activity of TKIs, both in vitro and in vivo." (PMID 28903416, 2017). "IL-6 and GM-CSF are two known factors regulating MDSC expansion associated with tumor conditions." (PMID 29070836, 2017). "In addition, tumor clinical samples containing significantly higher levels of IL-6 protein compared to those of control tissues and a higher IL-6 mRNA, correlate with poor patient survival." (PMID 28927416, 2017). "We wondered whether the reduction of IL-6 in mouse samples was a direct effect on tumor cells or was an indirect effect on inflammatory cells." (PMID 28088791, 2017). "The levels of IL‐1, TNF‐α and IL‐6 in the tumour were also detected." (PMID 28444871, 2017). "Elevated pro-inflammatory cytokines such as IL-6 in the tumor-suppressive microenvironment and chronically infected patients may also contribute to an increased number of senescent T-cells." (PMID 28881756, 2017). "Moreover, TNF and IL-6 directly control and contribute to tumor promotion in early lesions of ApcMin/+ mice by inhibition of apoptosis and up-regulation of angiogenic mediators." (PMID 28881611, 2017). "Prophylactic treatment with Losartan resulted in an anti-inflammatory response mediated by reduced IL-6 and TNFα production, which prevented the differentiation of tumor stroma and epithelial cell EMT, and attenuated the malignant transformation of DCIS to IDC." (PMID 28416734, 2017). "Additionally, IL-6, a multifunctional inflammatory cytokine produced by CAFs and TAMs, has also been shown to play important roles in tumor progression." (PMID 28114366, 2017).
tumor (continued). "We had previously shown iNOS was associated with elevated tumor expression of IL-8 in ER-negative breast cancer and was inducible by DETA/NO in TNBC cell lines, and that iNOS inhibition decreased TNBC tumor xenograft IL-6 and IL-8 mRNA expression." (PMID 29113326, 2017). "While AMPK activation by systemic IL-6 also corresponds with mTORC1 suppression in tumor-bearing mice, AMPK inhibition could rescue IL-6-induced suppression of mTORC1 signaling in C2C12 myotubes." (PMID 29375734, 2017). "The tumor cells express IL-6, which is an important factor in the development of HHM." (PMID 29056680, 2017). "In addition, IL-6 also stimulates T lymphocyte proliferation, influences growth, differentiation, and migration of tumor cells, and stimulates angiogenesis." (PMID 29268708, 2017). "In vivo treatment with IL-6 also promoted tumor formation and increased tumor nodules in mice." (PMID 28388577, 2017). "Recently, a growing body of literature claimed that cytokines are not only produced by the immune cells present in the tumor microenvironment, the autocrine origin of some inflammatory cytokines, especially IL-1, IL-4 and IL-6, was observed in large range of solid tumors." (PMID 28927416, 2017). "Moreover, IL-6 promotes tumor migration and invasion, and its inhibition by blocking antibodies significantly reduces these effects." (PMID 28915700, 2017). "In a Th1 microenvironment, proinflammatory cytokines (e.g., IL-6 and IL-1) may contribute to tumour eradication by attracting leucocytes from the circulation and by increasing CD4 + T cell activity." (PMID 29089667, 2017). "Interestingly, lower intratumoral IL-6 levels –an inhibitor of Natural Killer (NK) cell cytotoxity- were observed in both transgenic and rshCD5-treated WT mice and the anti-tumor effect was abrogated by mAb-induced NK cell depletion." (PMID 29296231, 2017). "The pro-inflammatory proteins (RANTES CXCL5, IL6) may result from the “host” response tumor cells, mainly injured endothelial cells, as reflected by the high prevalence of endothelial EVs." (PMID 28968987, 2017). "Tumor cells via IL-6 may exert an indirect effect on thrombocytosis and platelet uptake of free VEGF that may facilitate the transport of VEGF to the site of tumor cell-EC interaction." (PMID 28681240, 2017). "COX-2 and IL-6 mRNA expression was clearly suppressed in the polyp portions of the intestines of Min mice, which may have affected local tumor growth and may explain the decreases in polyp numbers elicited by EM treatment." (PMID 28584401, 2017). "Our findings strongly support a recent hypothesis where the inflammation amplifier was activated by the stimulation of cytokines, such as TNF-α and IL-6, resulting in the subsequent expression of tumor-related genes such as HIF1-α and SOD-230." (PMID 28801561, 2017). "One explanation for the association of a favorable response with the inactivation of SHP gene expression could be that therapeutic agents, particularly thalidomide, act through the inhibition of cytokines such as IL-6 that sustain tumor growth and survival." (PMID 28369102, 2017). "Considering the inhibitory effect of IL-6 knock-down on PC-3 cell growth in vitro and in vivo, and the importance of IKKε in the regulation of IL-6 secretion in PC, we studied the role of IKKε on PC-3 cell proliferation and tumor formation." (PMID 27577074, 2017). "In addition, PERK-mediated upregulation of fibroblast growth factor 2 (FGF2), vascular endothelial growth factor (VEGF), and interleukin-6 (IL-6) and downregulation of antiangiogenic cytokines remarkably promote tumor growth and vascularization." (PMID 29430279, 2017). "Furthermore, tumors that do not arise because of chronic inflammation appear to later develop an IL-6-rich microenvironment, which supports tumor progression and metastasis." (PMID 28529938, 2017).